PTH (parathyroid hormone)
Diseases named in the same sentence as PTH in open-access papers (continued):
Sharing a sentence is not in itself a finding about the gene and the disease.
cognitive decline (11 papers, 2009 to 2024). "While these data provide evidence for an association between elevated PTH levels and cognitive decline, further studies are needed to better elucidate the exact mechanism of cognitive decline in those with SHPT." (PMID 38707996, 2023). "Nine studies assessing the relationship between SHPT and cognition have been published in the last two decades, each showing that elevated parathyroid hormone (PTH) levels were associated with cognitive decline." (PMID 38707996, 2023). "Only one study adjusted for ionized calcium as a potential confounder though the association between PTH and cognitive decline at one and five years remained." (PMID 26010883, 2015). "It is of interest to notice reports that abnormal PTH levels may be associated with neuronal calcium imbalance, cognitive decline, and neuroinflammation." (PMID 36918976, 2023). "As such, the PTH threshold that is associated with cognitive decline is unclear, and the trajectory of cognitive decline is unknown." (PMID 38707996, 2023). "Elevated PTH concentrations are associated with cognitive decline and may increase tissue aluminum loads which is a factor in the pathogenesis of AD." (PMID 22629218, 2012). "Such a threshold would give providers a target for PTH levels to improve or prevent cognitive decline." (PMID 38707996, 2023). "It has been proposed that of the many uremic toxins normally excreted through the kidneys, uric acid, parathyroid hormone (PTH) and indoxyl sulfate are most likely to contribute to the development of cognitive decline in individuals with CKD." (PMID 34867762, 2021). "The connection between elevated PTH and cognitive decline is becoming well studied." (PMID 19825157, 2009). "Therefore, it seems reasonable to speculate that the cognitive decline in patients with PHPT might be proportionally interrelated with PTH level." (PMID 37923800, 2023). "This suggests that PTH elevation may precede cognitive decline." (PMID 26010883, 2015). "Cognitive decline is common among patients with PHPT, which is characterized by elevated PTH and serum calcium." (PMID 37923800, 2023). "The relationship between PTH and CI remains inconclusive, a large population-based cohort study that found no independent influence of PTH on cognitive decline over a 20-year period." (PMID 39717345, 2024). "Additionally, the studies assessing the impact of KT on cognitive function do not account for PTH levels, and thus the association between post-transplant SHPT or THPT and cognitive decline is unclear." (PMID 38707996, 2023).
essential hypertension (11 papers, 2011 to 2025). Hypertension that presents without an identifiable cause. "The relationship between the RAAS and PTH is significantly positive, as patients with PA exhibit higher PTH levels compared to secondary aldosteronism and primary hypertension patients." (PMID 32973674, 2020). "In 223 middle-aged, nondiabetic, primary hypertensive patients free of major cardiovascular and renal complications, we measured 25(OH)D and parathyroid hormone (PTH) and assessed subclinical carotid arteries changes by B-mode ultrasonography." (PMID 39940336, 2025).
Glucose intolerance (11 papers, 2013 to 2025). Glucose intolerance (GI) can be defined as dysglycemia that comprises both prediabetes and diabetes. "This is surprising; previous studies associated elevated PTH levels with glucose intolerance and insulin insensitivity." (PMID 27362844, 2016). "The secondary high parathyroid hormone (PTH) concentration and increased inflammatory markers (Zhou and Hyppönen, 2023) associated with vitD deficiency may also cause glucose intolerance." (PMID 40625194, 2025). "However, contrary to our findings, most animal studies and human studies investigating the association between PTH and glycemic metabolism showed that it was the evaluated PTH that was associated with glucose intolerance, beta cell dysfunction, and dysglycaemia." (PMID 33833796, 2021). "Clinically, states of excess PTH secretion (e.g., P/SHPT) are associated with impaired insulin secretion and glucose intolerance, which improve after PTX—suggesting an occult, yet reversible, PTH-mediated effect on pancreatic islet function." (PMID 41227247, 2025). "Possible contribution of PTH to glucose intolerance is also supported by observation of significant direct correlation of serum PTH levels with G-AUC." (PMID 35057492, 2022).
hypovitaminosis (11 papers, 2013 to 2025). "We further found that hypovitaminosis Din PTH-responders was associated with higher 90-day mortality than was the same condition in non-responders." (PMID 24073266, 2013). "Furthermore, laboratory data revealed the highest mean serum levels of PTH and the lowest levels of Ca and P among patients with severe vitamin deficiency." (PMID 32821633, 2020). "In the PA subgroup, all patients had mildly elevated PTH levels (<100 pg/mL), and three out of seven had low vitamin D levels, while another three were on vitamin D treatment for a severe preoperative hypovitaminosis." (PMID 40507262, 2025). "Prolonged hypovitaminosis (25(OH)D < 50 nmol/L) is known to trigger a compensatory increase in PTH with its undesirable acceleration in bone resorption, alongside other recognized adverse skeletal and non-skeletal consequences." (PMID 36356037, 2022). "Notably, 60% of the individuals had hypovitaminosis (25(OH)D < 30 ng/mL), and 62% had elevated PTH levels (>40 pg/mL)." (PMID 41301518, 2025). "Hypovitaminosis D may generally interfere with the proper function of insulin receptors and GLUT-4 in target tissues, probably via increasing parathyroid hormone levels." (PMID 36209084, 2022).
insomnia (11 papers, 2010 to 2025). A sleep disorder characterized by difficulty in falling asleep and/or remaining asleep. "Elevated parathyroid hormone levels are also associated with poor sleep quality, and parathyroidectomy has been found to improve insomnia substantially." (PMID 36873448, 2023). "That study also associated the presence of insomnia with longer duration of dialysis (>12 months) in patients undergoing dialysis in the morning and in those with high levels of parathyroid hormone." (PMID 28912971, 2017). "Our study found no significant influence of sodium, potassium, calcium, phosphorus, vitamin D3, PTH, and hemoglobin on insomnia." (PMID 39099947, 2024). "Insomnia in ESRD patients is affected by a variety of factors, including elderly age, dialysis vintage and a higher parathyroid hormone level, in which, patients treated with maintenance hemodialysis (MHD) have ranked insomnia as one of the major issues that reduce their quality of life." (PMID 40298061, 2025). "However, biochemical variables like sodium, potassium, calcium, phosphorus, vitamin D3, PTH, and hemoglobin do not seem to affect poor sleep quality and insomnia." (PMID 39099947, 2024). "However, biochemical variables like sodium, potassium, calcium, phosphorus, vitamin D3, parathyroid gland hormone (PTH), and hemoglobin do not seem to affect poor sleep quality and insomnia." (PMID 39099947, 2024).
type 1 diabetes (11 papers, 2013 to 2025). "Additionally, daily PTH administration in mice with type 1 diabetes caused an elevation of trabecular bone density in the tibiae to levels of normal mice." (PMID 29544500, 2018). "Insulin deficiency in type 1 diabetes might play a role in reduction of serum PTH levels." (PMID 23865464, 2013). "In a study, healthy people and patients with type 1 diabetes inhibited plasma PTH secretion during an oral glucose tolerance test and an isoglycemic intravenous glucose infusion." (PMID 39791168, 2025). "In consistent to our study, Inukai and colleges’ evaluated OC, vitamin D and PTH in type 1 diabetes patients with nephropathy." (PMID 27826545, 2016). "Whether or not parathyroid hormone and/or magnesium intake modify the association between vitamin D and microvascular complications and CVD in type 1 diabetes needs to be further investigated." (PMID 26025465, 2015).
autosomal dominant hypocalcemia type 1 (10 papers, 2015 to 2026). "Activating mutation of the calcium-sensing receptor gene (CASR) reduces parathyroid hormone secretion and renal tubular reabsorption of calcium, defined as autosomal dominant hypocalcemia type 1 (ADH1)." (PMID 36812896, 2023). "The NPSP795 molecule (encaleret) increased plasma PTH levels in a concentration-dependent manner up to 129% above baseline in 5 patients with autosomal dominant hypocalcemia type 1 (ADH1)." (PMID 36382754, 2022). "Eneboparatide, a long-acting modified form of parathyroid hormone, increases serum calcium levels without increasing urine calcium in mice with autosomal dominant hypocalcemia type 1." (PMID 41712458, 2026).
celiac disease (10 papers, 2013 to 2025). An autoimmune genetic disorder with an unknown pattern of inheritance that primarily affects the digestive tract. "For disorders such as celiac disease there may be an issue with regards to intake and/or malabsorption of vitamin D; with Addison’s disease, glucocorticoid deficiency may lead to suppression of the parathyroid hormone-vitamin D axis." (PMID 23885887, 2013). "There was a significant difference between the children with celiac disease group and the control group in terms of the mean magnesium, parathyroid hormone and vitamin D levels measured in routine controls of all these patients." (PMID 40861047, 2025). "Patient 4 presented resistance to PTH, brachydactyly, psychomotor retardation, gastroesophageal and vesicoureteral reflux, celiac disease and subluxation of the temporomandibular joint." (PMID 30616679, 2019). "Moreover, celiac disease patients on GFD undergo a significant decrease in the parathyroid hormone (PTH) levels, together with a significant increase in the calcium and vitamin D concentrations, thus allowing adequate skeletal mineralization." (PMID 35269854, 2022).
hypophosphatemic rickets (10 papers, 2013 to 2024). Rickets due to low serum phosphate concentrations, the cause of which can be nutritional or genetic. "This, together with our findings regarding reduced growth in the INC group, is in accordance with the known INC feature of hypophosphatemic rickets, which is normally also known to be accompanied by low PTH levels." (PMID 38850407, 2024). "Phosphopenic rickets is initially commonly characterized by normal or slightly elevated serum PTH and low serum phosphorus." (PMID 36817604, 2023). "Patients with HHRH can be distinguished from those with other forms of hypophosphatemic rickets by their high 1,25 vitamin D levels in conjunction with low to normal parathyroid hormone and fibroblast growth factor 23 (FGF23) levels." (PMID 37908277, 2022). "High serum FGF23 levels in conjunction with elevated levels of PTH contribute to the pathogenesis of renal phosphate wasting and hypophosphatemic rickets." (PMID 32271147, 2020). "Serum PTH concentrations are normal or only slightly increased in patients with hypophosphatemic rickets, except in rare instances, such as in patients with HHRH who showed low normal o reduced serum PTH concentrations." (PMID 38706696, 2024). "By contrast, PTH levels are usually in the normal range in patients with phosphopenic rickets, but can be slightly elevated in patients with FGF23-driven phosphopenic rickets, as FGF23 suppresses 1,25(OH)2D levels, which in turn stimulates PTH secretion in the parathyroid glands." (PMID 34910242, 2022).
lymphoma (10 papers, 2014 to 2025). A malignant (clonal) proliferation of B- lymphocytes or T- lymphocytes which involves the lymph nodes, bone marrow and/or extranodal sites. "A previous immunohistochemical study revealed that lymphoma-associated macrophages are possibly a main source of ectopic PTH." (PMID 25435965, 2015). "Furthermore, a statistically significant association was observed between high PTH levels and previous lymphoma treatment." (PMID 34876084, 2021). "This conversion, which is typically tightly regulated in the kidney through PTH and serum calcium concentration, occurs in an uninhibited fashion by way of PTH independent extrarenal malignant lymphocytes in the setting of lymphoma." (PMID 26328223, 2014). "Endogenous active metabolite intoxication due to coexisting granulomatous diseases or lymphoma may be characterized by suppressed PTH (intact), decreased or normal 25(OH)D concentration, and elevated 1,25(OH)2D." (PMID 30294301, 2018).
primary aldosteronism (10 papers, 2014 to 2025). An endocrine disorder characterized by excessive production of aldosterone by the adrenal glands. "In addition to renin (activity) and aldosterone levels for calculation of ARR or AARR, analysis of parathyroid hormone may be of additional diagnostic value in primary aldosteronism." (PMID 27682153, 2016). "These authors reported for the first time a significant increase in PTH levels in patients with primary aldosteronism." (PMID 29056965, 2017). "Elevated parathyroid hormone in patients with primary aldosteronism may affect bone health, especially cortical bone, as there is a significant decrease in hip bone mineral density." (PMID 35148746, 2022). "Even in individuals without primary aldosteronism, higher serum aldosterone levels are independently associated with higher PTH levels." (PMID 28808443, 2017). "Patients with significant primary aldosteronism frequently present with elevated parathyroid hormone levels that may be due to increased renal and fecal calcium loss, metabolic alkalosis or direct effects on the parathyroid glands mediated by aldosterone." (PMID 27682153, 2016).
Cushing syndrome (9 papers, 2014 to 2025). Cushing's syndrome (CS) encompasses a group of hormonal disorders caused by prolonged and high exposure levels to glucocorticoids that can be of either endogenous (adrenal cortex production) or exogenous (iatrogenic) origin. "Mutated genes in TETs were enriched in several hormone-associated pathways such as insulin secretion; Cushing syndrome; parathyroid hormone; and thyroid hormone, as well as multiple classical tumor-associated pathways, including cAMP, Notch, PI3K-Akt, and WNT signaling pathway." (PMID 41388389, 2025). "We found that genetic alterations in TETs were enriched in multiple hormone-related pathways, including thyroid hormone, parathyroid hormone, insulin secretion, and Cushing’s syndrome." (PMID 41388389, 2025). "What’s more, both the glucocorticoid (Cushing syndrome) and parathyroid hormone have profound effects on the homeostasis of bone through multiple cellular and molecular mechanisms." (PMID 32269995, 2020). "The KEGG pathway enrichment analysis revealed that the genes were enriched in multiple signaling pathways related to hormone synthesis and secretion, including Cushing syndrome; insulin secretion; parathyroid hormone synthesis, secretion, and action; and thyroid hormone (P < 0.05)." (PMID 41388389, 2025). "The CON/CUMS pair showed enrichment in pathways related to Aldosterone synthesis and secretion, Arachidonic acid metabolism, Cortisol synthesis and secretion, Cushing syndrome, parathyroid hormone synthesis, secretion, and action, and Vascular smooth muscle contraction." (PMID 40444002, 2025). "Moreover, we observed more pronounced alterations in hormone-related pathways—including Cushing syndrome, aldosterone, insulin secretion, parathyroid hormone, and thyroid hormone—in patients presenting with PNS." (PMID 41388389, 2025). "Intact and whole PTH concentrations (measured in pmol/L), the ratio of whole to intact PTH concentrations, osteocalcin (ng/mL), and ICTP (ng/mL) concentrations and the urine NTX to creatinine ratio in dogs with hyperadrenocorticism and a hospital control population." (PMID 32582784, 2020). "In contrast, among patients without clinically apparent PNS, only Cushing syndrome, insulin secretion, and parathyroid hormone synthesis, secretion and action showed significant changes (P < 0.05), and none remained significant after FDR correction (P.adjust > 0.3)." (PMID 41388389, 2025).
hepatitis B (9 papers, 2012 to 2025). "These down-regulated DEGs included the estrogen signaling pathway, hepatitis B, viral carcinogenesis, parathyroid hormone synthesis, and the secretion and action pathway." (PMID 36504863, 2022).
multiple endocrine neoplasia type 1 (9 papers, 2017 to 2024). An autosomal dominant tumor predisposition syndrome caused by pathogenic variants in the MEN1 gene, characterized by an increased risk of tumors of the parathyroid glands, pituitary gland, and foregut neuroendocrine tumors (most commonly pancreatic islet cells). "The levels of PTH, serum calcium, glucagon and gastrin were measured, which were all in normal range excluding the clinical diagnosis of multiple endocrine neoplasia type 1." (PMID 38093965, 2023). "A mild elevated parathyroid hormone (PTH) level of 71.6 pg/mL (reference range 10–65) evoked the possibility of multiple endocrine neoplasia type 1 (MEN1)." (PMID 30518416, 2018). "Prolactin, parathyroid hormone (PTH), albumin, and calcium levels, as well as MRI of his brain were normal, ruling out multiple endocrine neoplasia type 1 (MEN-1)." (PMID 31234935, 2019). "Multiple endocrine neoplasia type 1 (MEN1) was excluded from her family history, and serum levels of both intact parathyroid hormone (iPTH) and calcium were within normal ranges." (PMID 29181825, 2017).
Myocardial fibrosis (9 papers, 2015 to 2025). "Elevated serum PTH concentrations have also been associated with increased expression of Ang II in the myocardium, contributing to myocardial fibrosis and upregulation of type III collagen protein." (PMID 37842376, 2023). "PTH receptors are present in cardiomyocytes, endothelial cells, and smooth muscle cells, and elevated PTH levels are related to myocardial fibrosis, calcification, and hypertrophy." (PMID 31385484, 2019). "SHPT lead to vascular calcification, myocardial fibrosis, and calcium deposition due to the effects of persistent elevated PTH levels, volume overload, renal anemia, and uremic toxins, which results in decreased myocardial contractility and the multiplication of cardiovascular risks." (PMID 40041461, 2025). "Excess PTH subsequently induces calcium overload and oxidative stress in cardiomyocytes and exacerbates the reduction in intra-mitochondrial adenosine triphosphate levels, resulting in necrotic cell death and myocardial fibrosis." (PMID 26622568, 2015). "Our findings suggest that the co-intervention of PTH and high salt can lead to an increase in blood pressure, heart weight, myocardial cell hypertrophy, LVH, and myocardial fibrosis levels in Sprague-Dawley rats." (PMID 37842376, 2023). "The concomitant intervention of PTH and high salt intake can instigate an escalation in blood pressure, LVH, and myocardial fibrosis levels in Sprague-Dawley rats." (PMID 37842376, 2023). "This study is designed to investigate the combined impact of PTH and salt on blood pressure, LVH, and myocardial fibrosis in rats." (PMID 37842376, 2023). "PTH levels were comparable between patients without and with replacement myocardial fibrosis (17.76 ± 7.80 pg/mL vs. 17.42 ± 6.49 pg/mL; p = 0.965) and were uncorrelated with all biventricular function parameters (p > 0.05 in all correlations)." (PMID 38132240, 2023). "Therefore, when high salt intake or PTH acts independently, it may necessitate high-concentration intervention, long-term exposure, or even the selection of genetically hypertensive rats to potentially demonstrate an increase in blood pressure, LVH, and the occurrence of myocardial fibrosis." (PMID 37842376, 2023).